RNU5A-3P (RNA, U5A small nuclear 3, pseudogene)
Gene: Small nuclear RNA gene on chromosome 8 (30,643,689 to 30,643,802, forward strand). Ensembl gene ENSG00000254172.
Homologues: Orthologues: chimpanzee U5 (98% identical), macaque U5 (92% identical), rabbit U5 (76% identical), mouse Gm23102 (69% identical). Paralogues in human: RNU5E-4P (82% identical), RNU5B-4P (80% identical), RNU5A-4P (75% identical), RNU5F-7P (75% identical), RNU5E-10P (75% identical), RNU5E-5P (74% identical), RNU5E-7P (74% identical), RNU5E-8P (74% identical), RNU5A-7P (73% identical), RNU5E-6P (73% identical), RNU5A-2P (71% identical), RNU5B-2P (70% identical), and 13 more.